TNF (tumor necrosis factor)
Diseases named in the same sentence as TNF in open-access papers (continued):
Sharing a sentence is not in itself a finding about the gene and the disease.
breast carcinoma (continued). "Moreover, toxicity against breast cancer cells strongly correlated with cytokine inhibition with p = 0.023 for IL-1β and p < 0.001 for TNF-α, IL-6, IL-8, and IL-10." (PMID 31581678, 2019). "Considering IL-1β and TNF-α effects in the proliferation of breast cancer cell lines, we decided to investigate the relation between the cytokine mRNA levels and survival of breast cancer patients using TCGA data retrieved from the Human Protein Atlas database." (PMID 31093512, 2019). "However, in the following years, recent studies reported that TNF-α significantly induces breast cancer metastasis via TNFα-activated mesenchymal stem cells (MSCs) in a lung metastasis model of murine breast cancer." (PMID 32695310, 2019). "This neutralisation of TNF as well as TNFR2 by using TNF antagonist drugs delivered through nanoparticles might be an effective therapeutic strategy on breast cancer cells." (PMID 31239840, 2019). "The serum TNF-α level is significantly elevated in breast cancer patients." (PMID 31500658, 2019). "TNFα, an activator of the transcription regulator NFκB is highly expressed in breast carcinomas." (PMID 31075141, 2019). "With a view toward improving complete response rates, we investigated whether the principle Th1 cytokines (IFN-γ and TNF-α) could act in concert with lapatinib to suppress activity of breast cancer lines in vitro." (PMID 30657766, 2019). "Taken together, these findings suggest that the effects of OA on the suppression of proliferation, migration, and EMT formation on breast cancer cells could be reversed by TNF-α." (PMID 31341911, 2019). "TNF-α is considered as a potential biomarker of breast cancer growth and prognosis." (PMID 31500658, 2019). "Furthermore, saturated fatty acids can activate NF-κB, leading TNF-α production that acts on the breast cancer cell proliferation, invasion, and metastasis." (PMID 31398937, 2019). "In our hands, the combination of IFN-γ and TNF-α could mimic, on cultured breast cancer lines, many of the effects observed in vaccinated individuals including cell death and suppression of HER-family oncodriver expression." (PMID 30657766, 2019). "For example, some studies have demonstrated that TNF-α-preactivated human bone marrow-derived MSCs suppressed the progression of lung tumors formed from breast cancer cells, while mouse bone marrow-derived MSCs preactivated with TNF-α promoted the tumorigenesis and metastasis of breast cancer." (PMID 31149015, 2019). "However, it is shown that TNF can promote the proliferation and migration of normal epithelial cell and breast cancer cells both at low doses." (PMID 31341911, 2019). "Furthermore, the mechanism underlying glucocorticoids blockade of E2-induced apoptosis is also mediated by selective suppression of NF-κB DNA-binding activity and subsequent inhibition of TNFα expression in LTED breast cancer cells." (PMID 31815253, 2019). "Additional studies are necessary to determine the role of TNFα in this breast cancer model." (PMID 31888216, 2019). "On these bases, we hypothesized that the blockade of TNF-α may enhance the antitumor effects of OA for breast cancer patients and this speculation warrants further investigation." (PMID 31341911, 2019). "Indeed, recent studies substantiated the involvement of TNFα–mediated downstream NFkB activation during MSC/breast cancer cell fusion." (PMID 31557960, 2019). "To elucidate the molecular mechanism whereby conditioned macrophages affect ERα+ breast cancer cells and induce estradiol-independent proliferation via TNF-α stimulation, we used chromatin cross-linking and ChIP assays to identify assembled protein complexes that operate on cyclin D1." (PMID 30736340, 2019). "A large body of evidence indicates that circulating inflammatory biomarkers, including interleukin (IL)-4, IL-6, IL-8, C-reactive protein (CRP), and tumor necrosis factor-α (TNF-α), may be associated with breast cancer risk." (PMID 31430979, 2019).
breast carcinoma (continued). "Both IL-6 and TNF-α are considered to be the best characterized tumorigenic cytokines that involved in the promotion, progression and metastasis of tumor, and also, co-expression of these two cytokines determines the extension and outcome of breast cancer." (PMID 31412862, 2019). "In addition, ubiquitin‐specific protease COP9 signalosome 5 (CSN5) induced by NF‐κB p65 is required for tumor necrosis factor alpha (TNF‐α)‐mediated PD‐L1 stabilization in breast cancer cells." (PMID 29992764, 2018). "In addition, our results clearly indicate that Tumor Necrosis Factor (TNF) induced GD3S over-expression in breast cancer cells via NFκB pathway." (PMID 29698439, 2018). "They found that macrophage-secreted tumor necrosis factor alpha (TNF-α) could enhance breast cancer cell intravasation due to impaired endothelial barrier function." (PMID 30424426, 2018). "Therefore, we investigated the ability of primary human MAIT cells to produce TNF-α in response to MDA-MB-231 breast carcinoma cells." (PMID 30208917, 2018). "Another possibility is that GDNF expression in tumors may be initiated by pro-inflammatory cytokines, such as tumor necrosis factor alpha (TNFα), to be transcribed in breast cancer cells." (PMID 29608602, 2018). "Furthermore, treatment of trastuzumab and pertuzumab-resistant breast cancer cells with TNF-α and IFN-γ restored sensitivity and induced senescence and apoptosis." (PMID 29796172, 2018). "It was previously shown that TNF/TGFβ treatment of mouse mammary carcinoma cells induced EMT and generated breast cancer stem cells with a claudin-low molecular subtype characterized by the expression of mesenchymal and stem cell-associated markers, and associated with a poor prognosis." (PMID 29698439, 2018). "The level of TNF-α was higher in premenopausal than postmenopausal women, and it is positively associated with the risk of breast cancer in premenopausal, but not in postmenopausal women." (PMID 30111758, 2018). "Similarly, E2 started to induce TNFα after 6 days of treatment and reached a peak after 12 days of exposure to E2 in another E2-deprived breast cancer cells, MCF-7:2A." (PMID 29531812, 2018). "Furthermore, cell from normal mammary epithelium and breast cancer cell lines expressed ICAM1 upon stimulation with the proinflammatory cytokines TNFα, IL1β and IFNγ." (PMID 30082828, 2018). "Multiple studies have established an immune-modulatory role for miR-146b, including suppression of IL-6 allowing p16-dependent tumorigenesis in breast cancer, as well as suppression of multiple other pro-inflammatory cytokines and chemokines such as TNF-alpha, IL-8, and IL-10." (PMID 30018734, 2018). "Furthermore, it has been observed that human breast cancer cell-derived exosomes induce the secretion of IL-6, TNFα, and CCL2 from both human THP-1 and murine RAW macrophage cell lines via the toll-like receptor 2/NF-κB signaling pathway." (PMID 29867925, 2018). "However, we found that breast MAIT cells that were exposed to E. coli-pulsed breast carcinoma cells produced only IL-17A and TNF-α." (PMID 30208917, 2018). "TNF is a major inflammatory cytokine shown to be highly expressed in breast carcinomas." (PMID 29671401, 2018). "Furthermore, it has been demonstrated in MDA-MB-231 cells, that TNF-α increased MMP-9 expression and activity by inducing AP-1 DNA binding activity, thus reinforcing the concept of a protumorigenic effect of TNF-α in breast cancer." (PMID 29202842, 2017). "Furthermore, previous literature reported high circulating levels of IL6 and IL8 in patients with BM, and that patients suffering from pain with advanced breast cancer have high systemic levels of the inflammatory mediators TNF, IL-1b, and IL6." (PMID 28903357, 2017). "Thus, we conclude that TNF-α can promote the growth of breast cancer through HBXIP in vitro and in vivo." (PMID 28938560, 2017).
breast carcinoma (continued). "Thus, our results uncovered a non-autonomously regulatory mechanism of YAP in cancer cells by environmental cues and provided a molecular basis for targeting TNFα-IKK-YAP/p65-HK2 pathway to effectively treat breast cancer cell metastasis." (PMID 28945218, 2017). "TNF-α presented radiotherapy- and chemotherapy-sensitizing effects against breast cancer cells." (PMID 28127258, 2017). "Although the clinical application of TNF-α has been restricted because of its toxicity, the use of tumor-targeted therapeutic strategies employing nanoparticles or tumor-homing peptides offer great promise for the treatment of breast cancer." (PMID 29202842, 2017). "In addition to TGFβ, cytokine tumor necrosis factor α (TNFα) also induces breast cancer cell migration and invasion by enhancing the stability of Snail, which is a major transcription factor governing the EMT program." (PMID 28356139, 2017). "Interestingly, breast cancer patients treated with chemotherapy had significantly elevated IL-6 and TNF-α levels after approximately 5 years off-therapy, compared with healthy controls, with an interaction between these two cytokines." (PMID 28377717, 2017). "Also, breast cancer patients had lower concentrations of adiponectin and higher concentrations of leptin, IL-6, IL-8, TNF-α, resistin and visfatin than controls." (PMID 29088874, 2017). "In addition, we measured the concentrations of G-CSF, IL-1β, IL-6, CCL4 and TNFα in the plasma of the mice with breast cancer." (PMID 28178994, 2017). "For instance, the fourth most upregulated gene, lipocalin 2, has also been reported to be oncogenic in both lung and breast cancers and could be stimulated by interferon-γ and tumor necrosis factor-α in murine subcutaneous adipocytes." (PMID 28629450, 2017). "Accordingly, we are interested in whether TNF-α promotes the development of breast cancer through up-regulating HBXIP." (PMID 28938560, 2017). "Next, we try to explore the mechanism by which TNF-α up-regulates HBXIP in breast cancer." (PMID 28938560, 2017). "However, TNF-α failed to work in MDA-MB-468 cells when TNFR1 was knockdown by siRNA, suggesting that TNF-α up-regulates HBXIP depending on TNFR1 in breast cancer cells." (PMID 28938560, 2017). "In the present study, we investigated whether TNF-α could enhance the effect of chemotherapy and radiotherapy against breast cancer cells." (PMID 28127258, 2017). "Indeed, emerging evidence suggests that TNF fuels the progression of breast cancer by promoting proliferation, transformation, angiogenesis, invasion, and metastasis, as well as being vital for the viability of TNBC cell lines." (PMID 28607534, 2017). "In this study, we are interested in the effect of TNF-α on HBXIP in breast cancer." (PMID 28938560, 2017). "Thus, we conclude that inflammatory cytokine TNF-α promotes the proliferation of breast cancer cells through activating its receptor TNFR1." (PMID 28938560, 2017). "TNF-α is a proinflammatory cytokine with opposing effects on breast cancer cells." (PMID 29202842, 2017). "In our present study, we investigate whether TNF-α could enhance the cytotoxicity of chemotherapeutics and radiotherapy against breast cancer cells." (PMID 28127258, 2017). "Together, similar to macrophage CM, TNFα treatment could activate YAP signaling in breast cancer cells." (PMID 28945218, 2017). "Interestingly, in preclinical and clinical studies in breast cancer, TNF-α has shown important antitumor activity alone and in combination with chemotherapy, radiation therapy and cryosurgery." (PMID 29202842, 2017). "High TNF-α could therefore promote breast cancer by this mechanism, which is likely to be more important in premenopause − before the fall in estrogen synthesis heralded by the menopause." (PMID 28983080, 2017). "In order to test whether raloxifene antagonized TNF-α, we treated MCF-7 breast cancer cells with TNF-α at 10, and 100 pg." (PMID 28770521, 2017).
breast carcinoma (continued). "Conversely, the overexpression of HBXIP could rescue the inhibition caused by STAT3 knockdown in the cells treated with TNF-α, suggesting that TNF-α promotes the proliferation of breast cancer cells through STAT3/HBXIP signaling." (PMID 28938560, 2017). "Likewise, TNF-α increased the cytotoxicity of chemotherapy (docetaxel, 5-fluorouracil, cisplatin) and radiotherapy against breast cancer in in vitro and in vivo studies." (PMID 29202842, 2017). "Also, in naïve breast cancer patients, high serum sTNFRs levels were found together with a trend toward higher plasma concentrations of TNF-α compared to controls." (PMID 29202842, 2017). "In breast cancer cells, TNF-α plays a key role in inflammation and cell apoptosis." (PMID 28184196, 2017). "However, upon treatment with honokiol (Group IV), mammary cancer bearing animals showed significant (p < 0.05) reversal in inflammatory cytokines levels of TNF-α, IL-1β, and IL-6." (PMID 28620301, 2017). "In addition to infiltrated immune cells, ER positive breast cancer cells also secrete TNFα, in response to E2 regulation, creating a positive feedback loop for E2 synthesis." (PMID 27160081, 2016). "This study demonstrates that the ethyl acetate fraction from E. humifusa Willd (EA/EuH) has a preventive effect on TNFα-induced invasive capability of highly metastatic MDA-MB-231 breast cancer cells through the inhibition of NF-κB-mediated MMP-9 gene expression." (PMID 27776550, 2016). "Furthermore, TNF stimulated neutrophil cytotoxicity against breast cancer cell lines and induced PRKCI expression in the subset of samples that had low basal expression of this gene." (PMID 28721376, 2016). "There is lack of association between the TNF-α T-857C polymorphism and colorectal cancer, cervical cancer, prostate cancer, and breast cancer." (PMID 28115787, 2016). "It was reported that TNF-α may promote breast cancer cell migration by inducing activation of the MAPK/ERK signaling pathway." (PMID 27464624, 2016). "Although TNF-α was also reported to be associated with self-reported memory complaints at baseline and longitudinally among breast cancer patients, the current study failed to establish an association between plasma TNF-α levels and cognitive impairment." (PMID 27701469, 2016). "Of note, 1,25(OH)2D3 treatment protects against TNF-α-induced VDR loss, suppresses TGF-β1-promoted increase in the migration capacity of cultured breast cancer cells, and inhibits lung metastasis in an orthotopic breast cancer mouse model." (PMID 26880977, 2016). "Inverse associations with breast cancer were seen in fully-adjusted models, for 2nd and 3rd tertiles of ox-LDL, OR (95% CI): 0.65 (0.47–0.90), 0.63 (0.45–0.89) respectively, p-trend = 0.01; and for the 3rd tertile of TNF-α, 0.65 (0.43–0.99), p-trend = 0.04." (PMID 27391324, 2016). "We tested whether IL1A, MCP-1, IL1RA, and TNF were capable of stimulating neutrophil cytotoxicity to determine whether the increased serum levels of these cytokines in breast cancer patients were directly related to the cytotoxic activity of neutrophils." (PMID 28721376, 2016). "In one study of 20 breast cancer patients and 23 healthy controls, left hippocampal volumes were reduced significantly and IL-6 and TNF-α concentrations elevated in the breast cancer group and lower left hippocampal volume was associated with higher circulating TNF-α and lower IL-6." (PMID 27047716, 2016). "The NFκB signaling pathway, which can be activated by TNF-α, is known to activate the expression of various genes involved in the process of tumor metastasis and growth and its inactivation suppress metastasis of breast cancer cells." (PMID 26888313, 2016). "The effect of morphine on the expression of VEGF in the co-culture of breast cancer cells with macrophages could be a consequence of TNF-α activation." (PMID 27514308, 2016).
breast carcinoma (continued). "Hence, the aim of this study was to evaluate the associations between pro-inflammatory cytokine gene polymorphisms namely, IL6-174 (rs1800795 G>C) and TNF-308 (rs1800629 G>A), and CACI among early-stage breast cancer patients in Singapore." (PMID 27701469, 2016). "In fact, WBC, which is recognized as a strong indicator of inflammation promoting cardiovascular events, was not correlated with ox-LDL, IL-1β and TNF-α, whereas these biomarkers yielded significant associations with breast cancer in the present study." (PMID 27391324, 2016). "Specifically in relation to breast cancer, TNFα was found to be highly expressed in breast tumors as compared with normal tissues, and patients with more advanced breast tumor phenotypes were shown to have elevated TNFα serum levels." (PMID 25762639, 2015). "TNFα expression significantly increases at the advanced stages of breast cancer." (PMID 26112140, 2015). "Simultaneous treatment of MCF7 and SUM52PE breast cancer cells with acidosis and hypoxia may induce the expression of inflammatory response genes such as tumor necrosis factor alpha (TNF-α) and tumor necrosis factor alpha-induced protein 3 (TNFAIP3)." (PMID 25988385, 2015). "It was reported that TNF-α can inhibit tumor growth in a breast cancer xenograft model." (PMID 26526388, 2015). "In addition, the TNF-driven pathway is constitutively activated in breast cancer, inducing NO and increasing and modulating oxidative stress in breast cancer cells." (PMID 26697139, 2015). "In addition, the elevated expression of pro-inflammatory cytokines such as TNFα, IL-1 and IL-6 in breast cancer is directly correlated with the metastatic behavior and progression of breast carcinomas." (PMID 26460736, 2015). "A recent study from our group has demonstrated that the presence of the primary tumor mass is determinant for the sustained proinflammatory systemic status found in women with breast cancer, which included high NO, enhanced oxidative stress, and augmented TNF-α." (PMID 26697139, 2015). "Furthermore, TNFα increased proliferation of human breast cancer cell line T47D through the intracellular signaling p42/p44 MAPK, JNK, PI3-K/Akt pathways and NF-kappa B transcriptional activation trigged by TNFα/TNFR1, TNFR 2 pathways." (PMID 26313265, 2015). "Therefore, enhanced carbonyl content, homocysteine, and TNF-α level seem to comprise a network communicating with each other in the breast cancer microenvironment." (PMID 26697139, 2015). "A recent study of nipple aspirate fluids obtained from patients with breast cancer indicated that high levels of cytokines, as TNF-α, are concomitant with augmented protein carbonylation and correlated with elevated systemic homocysteine, corroborating the present findings in tumor samples." (PMID 26697139, 2015). "TNFα is a major inflammatory cytokine shown to be highly expressed in breast carcinomas." (PMID 25762639, 2015). "BMDMs exposed to 4T1 mammary carcinoma-conditioned medium demonstrated enhanced production of pro-inflammatory cytokines tumor necrosis factor α, interleukin-6, and CCL2 in response to lipopolysaccharide (LPS) while production of interleukin-10 remained unchanged." (PMID 26177198, 2015). "Also, inhibition of ERK was associated with a decrease in autophagy and increased cellular sensitivity to tumor necrosis factor-α (TNF) in breast cancer MCF-7 cells." (PMID 26263881, 2015). "Moreover, a recent publication by Joan Massagué’s laboratory in breastcancer research showed that chemotherapeutics trigger the release of TNFα fromstromal cells and that this TNFα release helps breast cancer cells to survive andmetastasize." (PMID 28357238, 2014). "Interestingly, Pol II shows different dynamics during an acute TNFα-dependent transcriptional response in AC16 cells than it does during a rapid estrogen-dependent mitogenic response in MCF-7 breast cancer cells." (PMID 24564208, 2014).